PYY (peptide YY)
Diseases named in the same sentence as PYY in open-access papers (continued):
Sharing a sentence is not in itself a finding about the gene and the disease.
Obesity (continued). "The findings suggest that the interplay between DPP-4 and peptides such as PYY, NPY, and PP may play a critical role in the development of obesity- and diabetes-related gastrointestinal complications." (PMID 40142315, 2025). "Participants with healthy BMI (n=15), overweight BMI (n=29) and obesity (n=161) had samples taken fasting and 30 min post mixed liquid meal for analysis of glucagon-like peptide-1 (GLP-1), PYY, glucose-dependent insulinotropic polypeptide (GIP), insulin and glucagon." (PMID 38490484, 2024). "L. hilgardii, as a probiotic, also improved blood glucose and blood lipid metabolism and pancreas function by increasing the expression of gut-secreted hormones with anti-obesity and anti-diabetic actions, such as the glucagon-like peptide-1 (GLP-1) and peptide YY (PYY)." (PMID 39628717, 2024). "Interestingly, SCFAs, through GPR43 and HDAs, promote Peptide-YY (PYY) and GLP-1 expression and/or secretion, regulating food intake and preventing obesity." (PMID 39599740, 2024). "Currently, there are other dual GIPR/GLP-1R agonists available, such as GLP-1R/GR (glucagon receptor), GLP-1R/AR (amylin receptor), and GLP-1R/NPYR (peptide YY binds to neuropeptide Y receptors) and even triple agonists that can activate GIPR to treat obesity and T2DM." (PMID 38987789, 2024). "Further, these alterations in gut microbiota have been shown to promote important changes in satiation signals including gut hormones (leptin, ghrelin, GLP-1, peptide YY and CCK) and orexigenic and anorexigenic neuropeptides (AgRP, NPY, POMC, CART) that influence hyperphagia and therefore obesity." (PMID 37571301, 2023). "Hormones that control hunger, satiety, obesity, glucose, and maintain weight include leptin, ghrelin, cholecystokinin (CCK), oxyntomodulin (OXM), glucagon-like receptor-1 (GLP-1), insulin-like peptide-5 (INSLP-5), and peptide YY (PYY)." (PMID 36790719, 2023). "To expand, PYY stimulates hypothalamic Neuropeptide Y (NPY) receptors, and the long-term activation of these receptors can play a role in suppressing appetite and protecting pancreatic β cells, which is important for the prevention of diabetes and obesity." (PMID 36986268, 2023). "PYY and GLP‐1 can regulate intestinal cells to control gastric emptying and food intake, and stimulate insulin secretion to reduce blood glucose, which plays an important role in the prevention and treatment of obesity and diabetes." (PMID 37181324, 2023). "Overall, FB3-14 treatment might mitigate obesity and inflammation by mediating GPR41 to upregulate the serum PYY and GLP-1 levels by increasing the butyric acid content." (PMID 37836387, 2023). "Taken together, these results suggest that FB3-14 intervention increased GPR41 levels associated with higher levels of butyric acid content, increased the PYY and GLP-1 levels, and upregulated the mRNA relative expression of Adipor1 and Adiporq, thereby alleviating HFD-induced obesity." (PMID 37836387, 2023). "It has been seen that patients with reduced postprandial PYY release have lower satiety rates; the lack of PYY in mice results in hyperphagia and obesity." (PMID 37753211, 2023). "PYY promotes pancreatic β-cell proliferation and reduces apoptosis by activating hypothalamic neuropeptide Y1 receptors (NPYR1), and increases intestinal transit rate and satiety by activating NPYR2, which have obvious benefits for diabetes and obesity." (PMID 35784273, 2022). "However, the physiological role of PYY and GLP-1 in appetite and food intake regulation seems well-established by now, and the decreased secretion in obesity would therefore seem to contribute negatively to the condition." (PMID 35990325, 2022). "Thus, we cannot exclude that the absolute number of CCK-, PYY- and GIP-positive cells is enhanced in obesity." (PMID 33037328, 2021).
Obesity (continued). "Additionally, post-prandial release of hormones is altered, with lower circulating levels of PYY and GLP-1 reported in obesity, with levels remaining low after 10 weeks of sustained weight loss." (PMID 33924402, 2021). "Indeed, our study provides the novel finding that density of GLP-1-positive cells is reduced in jejunum in T2D individuals with severe obesity whereas CCK-, GIP- and PYY- producing cell densities remained unaffected." (PMID 33037328, 2021). "Furthermore, butyrate increased the production of GLP-1, peptide YY (PYY), and growth hormone; it also reduced appetite, activated brown adipose tissue, and diminished diet-induced obesity." (PMID 32019155, 2020). "Reduced circulating PYY and PP as well as elevated NPY levels which can be found in obese subjects give rise to a role in the pathophysiology of obesity." (PMID 33192409, 2020). "The purpose of this review is to summarise the physiological effects as well as the therapeutic implications of the gut hormones glucagon-like peptide-1 (GLP-1), oxyntomodulin, peptide YY (PYY), and glucose-dependent insulinotropic peptide (GIP) in the treatment of obesity and type 2 diabetes." (PMID 32436022, 2020). "In addition, five related genes of obesity (ADIPOQ, GCG, PCSK1N, TFAP2A, and PYY) were distributed in the top 25 over/underexpressed genes of cancer tissues." (PMID 33299884, 2020). "This is well demonstrated recently that individuals with overweightness and obesity who lost more weight after a long-term exercise intervention displayed an elevated postprandial rise in GLP-1 and total PYY, and a greater suppression in acylated ghrelin compared to those who lost less weight." (PMID 31275881, 2019). "In humans, fasting PYY and post-glucose GLP1 concentrations are inversely related to BMI, suggesting that low levels of PYY and GLP1 may pre-dispose to obesity." (PMID 31456748, 2019). "On the contrary to total PYY and total GLP-1, Douglas and colleagues reported that concentrations of acylated ghrelin were not modified after exercise in the participants who were lean, or in those with overweightness/obesity." (PMID 30131457, 2018). "Guelfi and colleagues also showed that a reduction in fat mass after resistance exercise training did not coincide with changes in acylated ghrelin, PYY, or PP concentrations in men with overweightess/obesity." (PMID 30131457, 2018). "Peptide-YY (PYY) and Glucagon-Like Peptide-1 (GLP-1) play important roles in the regulation of food intake and insulin secretion, and are of translational interest in the field of obesity and diabetes." (PMID 29311617, 2018). "Thus, HBG feeding suppressed the appetite and improved insulin sensitivity by increasing plasma levels of PYY and GLP-1, thereby inducing resistance to obesity." (PMID 29698465, 2018). "The ginsenoside, Rb1, may treat obesity by modifying the serum content and mRNA expressions of neuropeptide Y (NPY), NPY Y2 receptor, and peptide YY (PYY)." (PMID 29234439, 2017). "This study provided the important information of the JAL2 effects to enhance GLP-1 and PYY secretion and the possibility that the herbal medicine mixture may be used as a therapeutic agent of T2DM and obesity." (PMID 27069493, 2016). "Thirdly, although our findings strongly suggest that PYY is not a significant player in determining obesity status, it must be acknowledged that our samples were collected in a fasted state." (PMID 24743402, 2014). "Considering the power of the present study, with over 2000 subjects, our results indicate that circulating PYY concentration is not likely a significant factor affecting obesity status at the population level." (PMID 24743402, 2014). "Although the primary objective of this study was not investigating PYY and obesity status, their results are consistent with our current findings." (PMID 24743402, 2014).
Obesity (continued). "In summary, peripheral hormonal signals released from the GI tract (ghrelin, PYY, GLP-1, and CCK), pancreas (insulin), and adipose tissue (leptin) constitute a key component in the gut-brain axis-mediated control of appetite, energy expenditure, and obesity." (PMID 25412152, 2014). "Given PYY’s anorexigenic functions, it is not surprising that multiple studies have shown dysfunctional PYY signaling in obesity." (PMID 26237477, 2014). "High amylose starches have potential of controlling high-fat diet-induced obesity by modulating hepatic fatty acid oxidation while RS induces increase in the levels of anti-diabetic hormones i.e., glucagon-like peptide-1 (GLP-1) and peptide YY (PYY)." (PMID 23822656, 2013). "Anorexic conditions and bariatric surgery for obesity influence circulating levels of PYY and have a negative impact on bone mass, but the precise mechanism behind this is unclear." (PMID 22792209, 2012). "Studies in humans and animals have shown that administration of CCK, PYY, GLP-1, and NMB could decrease food intake but administration of ghrelin and NPY leads to obesity." (PMID 21390334, 2011). "Unlike GLP-1, the elevated levels of PYY post-surgery may contribute to longer-term improvements in obesity and glucose tolerance, highlighting its substantial and lasting role in weight reduction compared to GLP-1." (PMID 40500780, 2025). "This reduction in FFAR3, due to the intestinal dysbiosis characteristic of obesity, compromises the bacterial production of SCFA and its ability to activate this receptor, thus affecting energy homeostasis and the secretion of intestinal hormones such as PYY and GLP-1." (PMID 41149616, 2025). "Some studies report lower fasting and post-meal PYY levels in obesity, while others do not." (PMID 41150735, 2025). "Moreover, concomitant changes in hunger and satiety hormones have been reported in individuals with obesity, including increased fasting and postprandial ghrelin levels, along with decreased postprandial glucagon-like peptide 1 (GLP-1) and peptide YY (PYY) levels." (PMID 41190331, 2025). "Ongoing research and innovative approaches, including ghrelin receptor modulators, stable PYY analogues, positive allosteric modulators for CCK, and advanced amylin analogues or DACRAs, showcase the potential for more effective and targeted anti‐obesity medications." (PMID 39016695, 2024). "Some studies were also conducted in patients with obesity or metabolic syndrome, showing that acute administration of β-glucan enriched foods dose-dependently increases PYY, increases CCK without affecting ghrelin, or decreases GIP without affecting insulin, GLP-1, or ghrelin." (PMID 36832775, 2023). "Whereas, in the intervention with yeast beta-glucan, no metabolic effects were observed, the combination of RS with long-chain inulin increased energy expenditure and circulating PYY, and decreased postprandial glucose levels in lean men, but not in men with prediabetes and overweight/obesity." (PMID 37529001, 2023). "For example, one single-blinded study shows that a subcutaneous infusion of hormones including PYY, GLP-1, and oxyntomodulin (OXM) at a dose of 4/4/0.4 pmol/kg/min for 4 weeks significantly reduces body weight and improves glucose tolerance in patients with obesity and diabetes." (PMID 36141228, 2022). "Furthermore, authors examined the effects of bacterial supplementation on the colonic gene expression of Glucagon-like peptide-1 (GLP-1) and Peptide YY(PYY), which are the intestinal hormones with appetite suppressing and anti-diabetic plus anti-obesity properties." (PMID 34065217, 2021). "Future studies need to measure leptin in conjunction with the other appetite-regulating peptides (acylated ghrelin, PYY, GLP-1, CCK and PP) to enable a better understanding of how exercise-induced responses to appetite-regulating hormones might differ in obesity." (PMID 32729763, 2020).
Obesity (continued). "Moreover, due to its nauseating effect at higher doses, PYY has not been pursued as an anti-obesity target." (PMID 30662430, 2018). "In addition to GLP-1, pancreatic polypeptide (PP) and peptide YY (PYY)—peptides of gut origin affecting the gastrointestinal tract—have central anorexigenic effects (gut-brain peptides) and have been evaluated as possible treatments for obesity." (PMID 28820912, 2017). "Irrespective of this, promotion of PYY secretion may act to prevent obesity in these offspring early in life and therefore promote a healthier metabolic phenotype during adulthood." (PMID 26493953, 2015). "The first important finding from the present study is that circulating PYY was not significantly different among normal-weight, overweight and obese participants and these findings were consistent whether obesity status was defined either by %BF or BMI." (PMID 24743402, 2014). "However, GPR43 activation by increased SCFAs increased the number of the PYY-producing cells and PYY expression, which might be an effective therapeutic target for obesity but not T2D." (PMID 38055342, 2024). "Similarly, FFA2 is also thought to stimulate the release of PYY, so the absence of the receptor in the intestine might lead to decreased gut motility and reduced satiety, ultimately resulting in an increase in obesity." (PMID 38032704, 2024). "Previous findings indicate that longer duration MICT sessions (i.e., 60–90 min) are associated with higher total PYY concentrations in lean individuals, while our study and a previous study indicate active PYY does not increase in response to MICT in individuals with obesity." (PMID 39263536, 2024). "Moreover, bacterial supplementation with A. muciniphila led to increased mRNA levels of Peptide YY (PYY) and a significant upregulation of Glucagon-like peptide-1 (GLP-1) gene expression, both of which are intestinal hormones with appetite-suppressing, anti-diabetic, and anti-obesity properties." (PMID 39339675, 2024). "Higher fasting PYY and greater postprandial secretion are noted in non-obese individuals compared with obese individuals, suggesting that a reduced feedback from PYY might be a key mechanism for obesity." (PMID 37753211, 2023). "Additionally, epigallocatechin-3-gallate changes fatty acid uptake, fat production, and the expression of metabolism related regulatory genes in adipose tissue to reduce the occurrence of obesity, and the increase of GLP-1 and PYY levels might be involved in this regulatory process." (PMID 31195699, 2019). "The role of these hormones in obesity pathogenesis is not yet delineated but peripheral infusion of ghrelin is shown to promote food intake in humans and decrease fat oxidation and promote adiposity in animal models, whereas infusion of PYY and GLP dampens appetite and food intake in humans." (PMID 27313876, 2016). "For obesity treatment, this strategy may prove to be a more an effective strategy to reduce food intake than monohormone treatment, since the stimulation of GLP-1 secretion should lead to simultaneous release of the costored anorectic hormones CCK, glicentin, oxyntomodulin, and PYY, as reviewed." (PMID 24525020, 2014). "In healthy participants without obesity, performing exercise prior to a PKU meal has no impact on postprandial GLP-1, PYY, EE and appetite." (PMID 40410377, 2025). "In the present study, a strong correlation was identified between PYY mRNA and DPP-4 expression in patients with obesity, both with and without type 2 diabetes." (PMID 40142315, 2025). "The aim of this study was to investigate the impact of a single exercise session conducted prior to PKU-type meal on postprandial PYY, GLP-1, GDF-15, appetite and fat oxidation in a healthy population without obesity." (PMID 40410377, 2025).
Obesity (continued). "In addition, factors such as GLP1/PYY and TGR5 may also play a role in the anti-obesity effect of L. acidophilus H-68, and we plan to explore the potential mechanisms of L. acidophilus H-68 or other novel anti-obesity probiotics in depth from these dimensions in the future." (PMID 38731751, 2024). "This is in line with a previously published paper from our group showing that PYY postprandial response is poor in class I obesity compared with individuals without obesity, and completely absent in class II and III obesity." (PMID 36416279, 2023). "However, some researchers did not observe a significant difference in fasting PYY levels or postprandial PYY levels or following an OGTT between individuals with and without obesity." (PMID 41575482, 2026). "However, In our cohorts fasting and postprandial GLP-1 and PYY were not altered in obesity; therefore, it is unlikely overexpression of RGS9 represents a universal pathophysiological process in obesity." (PMID 39142076, 2024). "Moreover, two studies investigated the effects of exercise on appetite control in people with obesity, and found neither 60 min of MICT at 65% V̇O2max23 or 60 min of MICT at 70% HRmax changed active PYY in people with obesity or overweight." (PMID 39263536, 2024). "Here we show that partial DGAT1 deficiency in mice suppressed postprandial triglyceridemia, led to elevations in glucagon-like peptide-1 (GLP-1) and peptide YY (PYY) only following meals with very high lipid content, and did not protect from diet-induced obesity." (PMID 23336002, 2013). "This study found that, in a healthy population without obesity, acute exercise of moderate intensity conducted 1 h prior to a typical PKU meal (comprised of PKU special low protein foods, a protein substitute and natural free protein foods) had no impact on postprandial responses of GLP-1 and PYY." (PMID 40410377, 2025).